DLG1 (discs large MAGUK scaffold protein 1)
Diseases named in the same sentence as DLG1 in open-access papers (continued):
Sharing a sentence is not in itself a finding about the gene and the disease.
infection (8 papers, 2011 to 2024). The state of being infected such as from the introduction of a foreign agent such as serum, vaccine, antigenic substance or organism. "The propagation of the virus was more efficient in Dlg1- cells, with 40% more infected cells seven days-post infection (dpi), indicating that Dlg1 affects the replication of HIV-1 in T cells." (PMID 22272285, 2012). "HIV-1 yield during infection was followed in Dlg1+ and Dlg1- Jurkat T cells infected with HIV-1 by measuring by ELISA at different times the levels of p24 released in the supernatants." (PMID 22272285, 2012). "Finally, the drosophila discs large protein (Dlg1/hDlg/SAP97), another negative regulator targeting a very late stage of infection, was described." (PMID 32823718, 2020). "Thus, Dlg1, IQGAP1 or IMP1 are Gag-binding proteins that negatively regulate the late stage of infection, making them promising targets to block HIV-1 infection." (PMID 32823718, 2020). "Interestingly, a recent study showed that ZO1 was mislocalized during infection with AI viruses carrying the consensus -ESEV- PL motif (analogous to PLI), as a consequence of the interaction between NS1 and Dlg1." (PMID 22110760, 2011). "OG1RF infection did not modulate dlg-1, ajm-1, or let-413 expression." (PMID 26769134, 2016). "We also expanded our understanding of Salmonella’s interaction with ARHGEF26, finding that S. Typhi, but not S. Typhimurium uses ARHGEF26, DLG1 (also known as SAP97) and SCRIB (also known as Scribble) for SopB- and SopE- mediated infection of HeLa cells." (PMID 34242364, 2021). "Co-culture assays and quantitative cell-to-cell HIV-1 transfer analyses show that Dlg1 depletion does not modify transfer of HIV-1 material from infected to target T cells, or HIV-1 transmission leading to productive infection via cell contact." (PMID 22272285, 2012).
psychiatric disorder (5 papers, 2012 to 2025). A disorder characterized by behavioral and/or psychological abnormalities, often accompanied by physical symptoms. "Although the patient's deletion is relatively small, it partly overlaps the canonical 3q29 deletion (defined between TFRC and DLG1 gene) and extends upstream, associating a different facial phenotype compared to the classic 3q29 deletion, nonetheless showing a similar psychiatric disorder." (PMID 31338352, 2019).
neurodegenerative disease (4 papers, 2014 to 2023). A disorder of the central nervous system characterized by gradual and progressive loss of neural tissue and neurologic function. "The other five genes, bound by Tau under HS conditions (as also Grm5), were chosen according to their implication in neurodegenerative diseases (Trex1, Dlg2, Dlg1, Xrcc6, Eif2a)." (PMID 30321409, 2018). "In contrast to DLG1, there is less evidence to suggest that DLG2 is contributing to CSVD/neurodegenerative disease." (PMID 37422595, 2023). "Therefore, we extended our assessment of CAP2, DLG1, and ADAM10 gene and protein expression levels to the post-mortem superior frontal gyrus (SFG) of patients affected by neurodegenerative diseases such as PD and AD." (PMID 35163460, 2022).
neurologic disease (1 paper, 2015). "SAFB1 mediated isoform-specific changes in ANK3, ANKS1B, SAP97 (DLG1), ADD2, KIF16B, and ELK3, as well as in genes linked to the cytoskeleton and/or synaptic function and the aetiology of neurologic disease." (PMID 26694817, 2015).
DLG1 also shares sentences with these, for which no sentence is quoted: Cognitive impairment (4 papers); Alzheimer disease (3); epilepsy (3); adenocarcinoma (2); Anxiety (2); endometrial cancer (2); osteosarcoma (2); age-related macular degeneration (1); Ataxia (1); autism spectrum disorder (1); autoimmune conditions (1); bipolar disorder (1); brain tumor (1); cerebral palsy (1); cognitive decline (1); cognitive disorder (1); craniorachischisis (1); cryptorchidism (1); cystic kidneys (1); developmental delay (1); dilated cardiomyopathy (1); esophageal cancer (1); esophageal squamous cell carcinoma (1); heart failure (1); Huntington disease (1); Hydroureter (1); Lewis body disease (1); liposarcoma (1); Macrocephaly (1); meningioma (1).
A further 21 diseases each share a sentence with DLG1 in 1 paper.